ZEB1 (zinc finger E-box binding homeobox 1)
Diseases named in the same sentence as ZEB1 in open-access papers (continued):
Sharing a sentence is not in itself a finding about the gene and the disease.
tumor (continued). "These facts reveal a complex signaling crosstalk in the PCC tumor microecology, but key among them may be the ZEB1 + tumor cells and IFIT1 + TANs." (PMID 38898490, 2024). "Therefore, this study focuses on exploring the correlations between CD73 and ZEB1, considering their impact on tumor progression." (PMID 38388432, 2024). "The expressions of AP-1, IRF4, Zeb1, and TGFβ in 4T1 tumor tissue are presented in Supp." (PMID 38355711, 2024). "While ZEB1 in tumor cells regulates metastasis and therapy resistance, its role in CAFs is largely unknown." (PMID 38937629, 2024). "Accordingly, Zeb1 expression in tumour cells might also be a useful predictive marker for future combination treatments inducing ferroptosis in highly aggressive cancers." (PMID 39009641, 2024). "Moreover, the review discusses the implications of EMT-induced transcription factors such as Snail, Zeb1, and Twist in modulating the sensitivity of tumor cells to ferroptosis, thereby affecting drug resistance and cancer treatment outcomes." (PMID 38469234, 2024). "Prognostic value of tumour-based E-cad, β-cat, Fascin, Snail, Zeb-1 and stromal PN in CRC samples." (PMID 38935747, 2024). "DNAJB9 promoted FBXO45-induced degradation of ZEB1 and reduced the tumor metastasis in TNBC." (PMID 38773471, 2024). "Notably, the knockdown of EndMT signature gene ZEB1 significantly abrogated the tube formation rate of HUVECs in the presence of tumour cells, suggesting the crucial role of ZEB1 in the process of EndMT and angiogenesis." (PMID 38778448, 2024). "Moreover, these FIB cells showed a significant increase in SNAIL1 and ZEB1 expression, whereas SNAIL1 has been linked earlier to triggering EMT during tumor progression." (PMID 39682709, 2024). "Therefore, when evaluating the role of ZEB1 in 3D tumor models one must consider its specific pathological mechanisms within a specific type of cancer." (PMID 38254117, 2024). "To clarify whether the inflammatory polarization in combination with the reduced collagen deposition of Zeb1-deleted CAFs affects tumor immune cell infiltration, we performed IHC analyses." (PMID 38937629, 2024). "However, ZEB2, the second member of the ZEB family, is also specific to the E-box-like sequence and has the same function in EMT and tumor progression as ZEB1." (PMID 38751602, 2024). "In contrast, MAPKAPK5-AS1 increases ZEB1 via adsorption of miR-429 to elevate tumor progression." (PMID 38733529, 2024). "Up-regulated the expression of IL-8, MMP2, MMP9, p-STAT3, and ZEB1 in tumor." (PMID 39906741, 2024). "Notably, the Zeb1-dependent pro-ferroptotic effect was also induced by TGFβ, the most prominent example of a tumour-environmental EMT activator, whose temporal and spatial availability triggers cancer cell plasticity." (PMID 39009641, 2024). "Finally, ZEB1 emerged as a hub TF by combining the regulatory network diagram with the actual expression profiles within tumor cells." (PMID 39193340, 2024). "Besides, SNAI1 is assumed as one of the most important factors concerning tumor invasiveness, while the down-regulation of ZEB-1 and TWIST is associated with tumor progression and poor prognosis." (PMID 39538371, 2024). "Even before overt tumor outgrowth, significantly increased CD8+ and FOXP3+ cell infiltration was observed (Fig. EV4F–H), suggesting that the acute inflammation triggers a compensatory regulation of the immune microenvironment upon Zeb1 loss in fibroblasts." (PMID 38937629, 2024). "In addition to protein-coding genes, ZEB1 is bound to promote tumor metastasis by regulating downstream lncRNAs." (PMID 38965605, 2024). "Decreases in memory B cells, CD8+ T cells, follicular T helper cells, monocytes, and M0 macrophages further support ZEB1 expression and may influence anti-tumor immunity in the TME and recruitment of TILs." (PMID 38672562, 2024).
tumor (continued). "These experiments verified our model predictions and therefore provide support that a ZEB1 activator and Rosiglitazone may be an effective combination of drugs for inducing the transition of metastatic tumor cells into adipose cells." (PMID 39258786, 2024). "Single checkpoint inhibitor therapies or combination groups demonstrated suppression of snail and E‐cadherin suggesting that there might be involvement of other EMT markers (examples include Twist and Zeb1) in the SCCVII tumor cell growth." (PMID 38686626, 2024). "Even though we demonstrate that the presence of NK cells activated ZEB1 in UM cells both in vitro and in vivo, the underlying mechanism in which these pro-metastatic NK cells triggered EMT and tumor invasiveness remain unclear." (PMID 38191418, 2024). "Furthermore, when the expression of ZEB1 increases, it represses E-cadherin to enhance the mobility of tumor cells." (PMID 38733529, 2024). "Moreover, SOX9 levels were correlated with ZEB1 expression as exemplified in the ZEB1high MM10 tumor." (PMID 38519642, 2024). "Upregulation of ZEB1 in cancer can lead to tumor metastasis." (PMID 38733529, 2024). "Zinc finger E-box binding homeobox 1 (ZEB1), a master transcription factor in the EMT program, is intricately linked to aggressive behavior, metastasis, treatment resistance, and poor prognosis across diverse tumor types." (PMID 38388432, 2024). "Immunohistochemical assessment of E-cadherin, β-catenin, Vimentin, ZEB-1 and Ki-67 was performed in each tumor and a semiquantitative estimation of the percentage of expression was fulfilled on the best marking area at high of the tumor invasion front." (PMID 39388828, 2024). "Notably, upon infusion of NK cells, WT xenografts show higher frequencies of ZEB1 and Ki67 positive tumor cells compared with 4-1BBL-KO xenografts." (PMID 38191418, 2024). "It is tempting to speculate that mesenchymal-like activation drives this dysfunctional adhesion in tumor ECs, induced by epithelial-mesenchymal transition (EMT)-associated transcriptional repressors including Snail, Slug, Twist-1/-2, and Zeb-1/-2." (PMID 38580870, 2024). "Damaged and diseased tissues, however, may express high ZEB1, particularly in the dividing cells of tumor and fibrotic tissues." (PMID 38822380, 2024). "Notably, RNA editing of miRNA-200 has been proposed as a novel oncogenic mechanism, and the overexpression of miR-200b reduces its tumor suppressive activity by regulating ZEB1, which is relevant." (PMID 39764127, 2024). "Tumor cell expansion, coupled with HIF-1α overexpression, promotes EMT, triggering loss of cell-to-cell adhesion through upregulation of EMT transcription factors, including Snail, Slug, Twist, and ZEB1." (PMID 38339408, 2024). "ZEB1, a core transcription factor involved in epithelial-mesenchymal transition (EMT), is associated with aggressive cancer cell behavior, treatment resistance, and poor prognosis across various tumor types." (PMID 38388432, 2024). "To determine whether the tumor suppressor signature and the inhibition of EMT associated with ZEB1 in Braf-mutant mouse models also occurred in patients with CRC, we retrospectively analyzed 41 BRAF-mutant mCRC according to their ZEB1 expression." (PMID 37870961, 2023). "Expression of ZEB1 was significantly associated with tumor diameter, tumor stages, LNM, and FIGO stages, but not with patients age, smoking and alcohol status, gross type, and tumor location." (PMID 37335710, 2023). "Our findings indicate that in gastrointestinal malignancies, further in vitro and in vivo validation is necessary to elucidate the mechanism of interaction between VIP and ZEB1 and to determine how VIP supports ZEB1-mediated EMT involved in tumor invasion and metastasis." (PMID 37444395, 2023). "Our results show that ZEB1 functions as a tumor suppressor in BRAF-mutant CRCs, highlighting the need to assess the mutational background of CRC before using therapies that inhibit the expression and/or function of ZEB1." (PMID 37870961, 2023).
tumor (continued). "Furthermore, ZEB1 loss in leukaemic stem cells accelerated AML progression, implicating ZEB1 as a tumour suppressor." (PMID 37408496, 2023). "In vivo miR-34a significantly inhibited tumor growth and reduced ZEB1 expression." (PMID 36982460, 2023). "Furthermore, the positive expression of ZEB1 is significantly correlated to tumor stage, LNM, and FIGO stages." (PMID 37335710, 2023). "Indeed, in previous studies, depletion of ZEB1 was reported to drive tumor cells from pEMT towards an epithelial phenotype." (PMID 37076857, 2023). "Moreover, beyond regulatory role of EMT, ZEB1 also participates in critical cellular functions which exerts great impact in tumorigenesis and tumor expansion." (PMID 36644609, 2023). "Overexpressing ZEB1 diminished miR-143-3p-mediated tumor-suppressive effects." (PMID 37827696, 2023). "It is worth noting that tumor cells 3 cluster exhibited high expression of mesenchymal markers (ZEB1, FN1, and VIM) compared to the other two tumor cell clusters, suggesting that this population of cells may have undergone epithelial-mesenchymal transition." (PMID 37007745, 2023). "MiR-34a and its role as a tumor suppressor was analyzed in the context of inhibition of ZEB1." (PMID 36982460, 2023). "miR-205-3p is a tumour suppressor that directly targets and degrades ZEB1." (PMID 37891744, 2023). "Both ZEB1 knockdown and miR-508 overexpression mediated tumor-suppressive effects on ccRCC cells." (PMID 37827696, 2023). "Specifically, overexpression of ZEB1 is associated with EMT, tumor invasion, and metastasis." (PMID 36982917, 2023). "Likewise, tumor dLNs from Zeb1-dcKO mice contained similar numbers of resident and migratory cDC1 compared to that from WT mice, but had slightly fewer resident cDC2." (PMID 37863917, 2023). "Back to METTL3, its oncogenic activity has also been linked to tumor formation in CRC where m6A methylation of lncRP11 increases its nuclear accumulation, drives Siah1 and Fbxo45 mRNA degradation, and prevents ZEB1 mRNA decay, thus, regulating EMT and liver metastasis." (PMID 37369946, 2023). "Consequently, LINC00667 and ZEB1 mRNA levels increased, whereas miR-143-3p level was lowly expressed in tumor tissues versus normal tissues (P<0.05)." (PMID 37827696, 2023). "Furthermore, positive immunohistochemical staining of both Ki‐67 and Zeb1 in tumor tissues was aggravated when Dio3os was knocked down, suggesting that downregulation of Dio3os promotes HCC in mice." (PMID 37271897, 2023). "ZEB1 is also a key transcription regulator involved in tumor progression." (PMID 36644609, 2023). "This study corroborates the oncogenic nature of LINC00963 in LUAD and reveals two novel mechanisms responsible for its pro-tumor activities: stabilizing Zeb1 to promote epithelial-mesenchymal transition (EMT) and delivering exosomes to induce M2 macrophage polarization." (PMID 36604626, 2023). "The ZEB1 and ZEB2 expression were associated with tumor grade and miRNA expression." (PMID 37627900, 2023). "However, splenectomised Zeb1-dcKO mice still had compromised tumor control compared to splenectomised WT mice." (PMID 37863917, 2023). "USP18 could promote tumor metastasis in esophageal squamous cell carcinomas via deubiquitinating ZEB1." (PMID 36644609, 2023). "Collectively, these data suggested that Zeb1 in DC was required for control of tumor growth, although the loss of Zeb1 in DC did not affect tumor infiltration of cDC1 despite selective reduction of splenic cDC1." (PMID 37863917, 2023). "Therefore, we investigated the relation between EMT status, ZEB1, and PD-L1 within spatial simulations implementing scenarios with short-range IFNγ spreading at the invasive front of a tumor." (PMID 37638024, 2023). "ZEB-1 regulates the inhibition of CDH1 which promotes the EGFR/ERK axis in tumor cells." (PMID 36740668, 2023).
tumor (continued). "However, data from Kröger and colleagues revealed that high levels of ZEB1 caused cells to complete an entire EMT and drove them into the M state which was incompatible with efficient tumor-initiating abilities." (PMID 38139138, 2023). "Immunofluorescence results indicated that ZEB1 and MYL9 were significantly co-located at the interface between tumor cells and CAFs, which may also indicate an interaction between MYL9 and ZEB1 in the tumor EMT or invasion process." (PMID 37926835, 2023). "ZEB1 contributed greatly to the EMT process of tumor metastasis." (PMID 37124931, 2023). "Another study of Hu revealed the pro-metastatic effect of lncRNAs in the TME of LUAD and they found that lncR00963 loaded in LUAD cell-derived extracellular vesicles fostered tumor growth and metastasis by facilitating Siah1 degradation but suppressing Zeb1 degradation." (PMID 37566767, 2023). "This relationship could be explained by the regulatory mechanisms of miRNAs, which confirm their role in tumor stem cell potential by migration, invasion, sphere formation, and ZEB1 expression assays." (PMID 36982993, 2023). "Interestingly, the M13HS tumor hybrids revealed a co-expression of the EMT transcription factors ZEB1 and SNAIL, possessed a higher fraction of ALDH+ positive cells, formed larger mammospheres and migration was induced by EGF." (PMID 38139138, 2023). "It has been reported that LINC00645 can induce the activation of EMT and enhance the migratory and invasive abilities of tumor cells by regulating the expression of miRNA-205-3p and its target gene ZEB1 through the induction of the reverse transforming growth factor TGF-β." (PMID 37968670, 2023). "ZEB1 could promote tumor cell migration, invasion, and metastasis by changing cell plasticity and mediating EMT mechanism." (PMID 36644609, 2023). "Furthermore, evidence also indicated that ZEB1 was involved in tumorigenesis and tumor expansion, as a ZEB1 knockout model resulted in diminished acinar-ductal metaplasia, which suggested ZEB1's involvement in pancreatic tumorigenesis." (PMID 37124931, 2023). "Additionally, NF-κB upregulates multiple transcription factors, such as Slug, ZEB1, and Snail1, which directly enhance tumor cell EMT, invasion, and migration." (PMID 37917013, 2023). "For example, by modulating and regulating various signaling pathways within the tumor microenvironment, such as tumor cell PD-L1 checkpoint expression by the miR-200/ZEB1 axis, miRNAs support or inhibit specific mechanisms from negatively affecting tumorigenesis." (PMID 36076930, 2022). "We confirmed these data by performing spheroid-formation assays, supporting the hypothesis that PTTG1/ZEB1 collaboration is needed for PTTG1 to carry out its effect on tumor progression, specifically through EMT-promoting activity." (PMID 36230799, 2022). "Moreover, ZEB1 itself was also significantly higher expressed in PM when compared to primary tumours." (PMID 35194192, 2022). "Assessment of the function of X-inactive specific transcript (XIST) revealed that it mainly represses miR-429, a tumor suppressor, and then results in a higher expression of ZEB1 and EMT via the critical axis of XIST/miR-429/ZEB1 and enhances tumor cell invasiveness." (PMID 36402997, 2022). "Indeed, SN-exo transfer dramatically reduced E-cadherin expression and boosted the expression of Vimentin and ZEB1, rendered tumor cells a mesenchymal, spindle-like morphology." (PMID 36302751, 2022). "Understanding the mechanisms that regulate ZEB1 ubiquitination levels may provide a promising strategy for targeting E3 ubiquitin ligases and deubiquitinating enzymes in the treatment of tumor progression and metastasis." (PMID 35454770, 2022). "Previous studies in carcinoma have shown that expression of EMT-TFs (notably ZEB1, SNAIL and TWIST1) is associated with the recruitment of immunosuppressive cells, including regulatory T cells, myeloid-derived suppressor cells and tumor-associated macrophages (TAMs)." (PMID 35432344, 2022).
tumor (continued). "In addition, the combined therapy was more effective than the individual treatments in reducing the number of Zeb1-positive cells, which are indicators of invasive cells, outside the gross tumor mass." (PMID 36221088, 2022). "Moreover, exposure of low-dose antiprogrammed cell death protein 1 (PD-1) antibody elicits tumor regression in and extends the survival of ZEB1-deleted mice." (PMID 35454770, 2022). "As we found that LINC00273 was involved in EMT, which is critical for tumor cell migration, through ZEB1 expression, we focused on the LINC00273 gene expression as a representative of common genes that were regulated by the p-PDHA1/PKM2 complex in transcriptional level." (PMID 35740278, 2022). "Both actions of ZEB1 functionally synergise as ZEB represses epithelial genes and tumour suppressors and promotes the expression of oncogenes and EMT inducers including TGFβ1 and PTPN14, both genes that encode proteins capable of initiating EMT in their own right." (PMID 35278142, 2022). "Furthermore, IL-17 influences the upregulation of the ZEB1-mediated NF-κB pathway as well as tumor cell migration through stimulation of EMT." (PMID 36402997, 2022). "ZEB1 regulates tumor radioresistance by deubiquitylation of USP7." (PMID 36499447, 2022). "The protein level of ferroptosis-related genes was verified by the HPA database and IHC test, leading to the discovery that the expressions of ALOX5, PEBP1, ACSL4, and ZEB1 proteins up-regulated in tumor tissues, and existed differences between tumor tissues and normal tissues." (PMID 36313708, 2022). "Our findings suggest that feedback loops for HER3 reactivation via ZEB1 may contribute toward tumor differentiation in DT and reversible ALK-rearranged NSCLC cells and reveal a novel DT system with MET related to HER3 activation in cancer." (PMID 35042943, 2022). "Other studies showed that ZEB1 could promote tumor development via recruiting IL6 and IL8 in the tumor microenvironment." (PMID 35342335, 2022). "Suppression of EMT by knocking down ZEB1 has been achieved in several studies, and inhibition of ZEB1 expression may prevent aggressive tumor progression." (PMID 36402997, 2022). "Therefore, the regulation of ZEB1 in tumor progression is highly dependent on the cellular and tissue context." (PMID 35454770, 2022). "ZEB1 increases tumor cell adherence to collagen through α1β1 integrin." (PMID 34874914, 2022). "However, SMAD4 has also been reported to trigger EMT through the induction of EMT-associated transcriptional factors Snail, ZEB1, and ZEB2, or to function as a tumor promoter." (PMID 36088360, 2022). "Furthermore, quercetin decreased the protein levels of p-GSK-3β (Ser 9), β-catenin and ZEB1 in tumor tissue." (PMID 36386155, 2022). "Tumor-derived extracellular vesicles containing miR-1290 via Grhl2/ZEB1/PD-L1 axis could promote the immune escape of cancer cells." (PMID 36405753, 2022). "Moreover, the activation of miR-590-3p, as well as miR-139-5p, prevented GBM tumor invasion by targeting ZEB1 and ZEB2 and inhibiting EMT." (PMID 36402997, 2022). "Notably, ectopic expression of ZEB1 significantly abolished the inhibition in tumor growth by Biochanin A and/or cisplatin." (PMID 36512117, 2022). "The cordycepin group, doxorubicin group and combined group could regulate the EMT process by regulating EMT markers (e.g., N-cadherin, E-cadherin, ZEB1, Twist1) and could inhibit the expression of proteins related to tumor migration." (PMID 35186504, 2022). "It is well known that EMT could promote tumor invasion and metastasis, and ZEB1 (Zinc finger E-box-binding homeobox) is a significant marker for the EMT process." (PMID 35342335, 2022). "We next analyzed MAPKAPK5-AS1, miR-429 and ZEB1 expressions based on tumor grade." (PMID 35468721, 2022).